ALB (albumin)
Diseases named in the same sentence as ALB in open-access papers (continued):
Sharing a sentence is not in itself a finding about the gene and the disease.
kidney damage (continued). "Nephropathy as assessed by microalbuminuria (albumin/creatinine ratio) at baseline was present in 32%." (PMID 23951331, 2013). "In order to detect nephropathy, measurement of total (24 hrs) urinary albumin or albumin/creatinin ratio in random urine samples is being recommended." (PMID 23843814, 2012). "In 24 hrs urine collections, amounts of protein and albumin were compared to calculate cut off point of exerted protein for nephropathy diagnosis." (PMID 23843814, 2012). "Treatment with DR significantly reduced the urinary albumin excretion and restored Ccr, which indicated that DR ameliorated the functional abnormalities of nephropathy in WFRs." (PMID 21949662, 2011). "As anticipated Akita mice developed hyperglycemia around 4 weeks of age and by 20 weeks of age Akita mice had all developed nephropathy on the control diet, as indicated by a roughly 10-fold increase in urinary albumin/creatinine ratios." (PMID 21533091, 2011). "The diabetic subjects were further subdivided according to their nephropathy status based on urinary albumin-creatinine ratio (ACR) and glomerular filtration rate (GFR)." (PMID 21031056, 2010). "In humans, aliskiren, in addition to losartan, was shown to significantly reduce the urinary albumin excretion rate compared with placebo in hypertensive patients with T2DM nephropathy." (PMID 20441574, 2010). "The presence of kidney damage is often indicated by increased urine albumin, which is present in approximately 9-14% of the adult U.S. population." (PMID 21054877, 2010). "Mice with adriamycin-induced nephropathy showed high urinary albumin/creatinine ratio levels that were unaffected by injection of vehicle." (PMID 20680961, 2010). "Nephropathy status was based on albumin excretion rate and retinal laser-treatment was used as an indication of severe retinopathy." (PMID 21110902, 2010). "Cisplatin induced nephropathy was assessed by measurements of blood urea nitrogen, albumin and creatinine levels." (PMID 19356226, 2009). "There was a significantly increasing trend of serum sialic acid with severity of nephropathy (71.6 ± 23.6 mg %) and degree of urinary albumin excretion (794.3 ± 805.9)." (PMID 17187674, 2006). "There was a significantly increasing trend of plasma and urine sialic acid with severity of nephropathy (P < 0.001) and with degree of urinary albumin excretion (P < 0.001)." (PMID 16092968, 2005). "Nephropathy was defined as urinary albumin-to-creatinine ratio (UACR) >30 mg/g." (PMID 42193477, 2026). "Indeed, HGA interference caused a false-positive proteinuria result leading to a diagnosis of the patient with nephropathy, which was later realized to be a misdiagnosis with the measurement of urine albumin in this case." (PMID 39836193, 2025). "AKU-related nephropathy should be evaluated with urine albumin measurement instead of protein." (PMID 39836193, 2025). "Moreover, TNF-α can induce cell apoptosis and necrosis, increase reactive oxygen species production, and increase albumin filtration, leading to kidney damage." (PMID 40824899, 2025). "In the mild nephropathy group, factors that were significantly associated with PDR compared to mild retinopathy included systolic (p=0.044) and diastolic blood pressure (p=0.009), urine albumin/CR (p=0.034), HbA1c (p=0.0094), and insulin use (p=0.0048)." (PMID 40822949, 2025). "Multiple factors may lead to reduced serum globulin, albumin, and total protein levels in cases of kidney damage induced by ATO and ZNPs." (PMID 41318635, 2025). "Our present finding suggests that puberty may be an additional factor in accelerating the development of the earliest stage of nephropathy, when albumin excretion is still in the normal range." (PMID 40414873, 2025). "Urinary albumin-to-creatinine ratio (UACR) is an established biomarker for assessing kidney damage, but recent studies suggest it may also reflect broader health risks." (PMID 40416385, 2025).
kidney damage (continued). "To further evaluate potential kidney damage, we measured daily albumin excretion." (PMID 39245782, 2024). "A useful biomarker for assessing kidney damage is the urine albumin-creatinine ratio (UACR)." (PMID 39090593, 2024). "Nephropathy screening was assessed using spot urine albumin/creatinine ratio and eGFR calculation." (PMID 38101939, 2024). "Testing for albumin in the urine as part of the basic diagnostics for suspected nephropathy did not reveal loss of kidney function." (PMID 39339010, 2024). "The detection of oxidized albumin provides further insights into the oxidative stress status in CKD, enhancing our understanding of the pathological mechanisms underlying the disease, particularly the interplay between oxidative stress and kidney damage." (PMID 38395806, 2024). "To confirm the evidence of kidney damage, we measured the albumin/creatinine ratio in urine." (PMID 39337535, 2024). "The spot urine (micro)albumin to creatinine ratio (UACR), measuring the levels of micro amounts of albumin compared to the amount of creatinine in the urine, serves as an early marker for kidney damage and correlates with 24-h quantitative proteinuria in glomerular diseases." (PMID 39272637, 2024). "Additionally, hyperglycemia promotes the leakage of protein (albumin) into the urine (proteinuria), an early indicator of kidney damage." (PMID 38893451, 2024). "Kidney damage was assessed by quantifying urinary albumin and creatinine secretion." (PMID 37736101, 2023). "A urinary albumin excretion increase, and a pathological albuminuria range predict the development of cardiovascular and kidney damage and increase the risk of death in the diabetic and non-diabetic general population." (PMID 37189791, 2023). "The panel noted that a spot urine test is the standard tool with which to balance convenience and accuracy, and that UACR, instead of urine albumin concentration, should be measured, because it demonstrates a stronger association with future renal events in people with T2DM and nephropathy." (PMID 37240509, 2023). "Also, increases in the concentrations of markers of kidney damage, such as urea and uric acid, and decreases in the level of blood plasma albumin and hemoglobin were observed in the blood, while the amount of daily protein present in the urine increased." (PMID 37685718, 2023). "Included studies used different biomarkers indicative of renal disease (nephropathy, proteinuria, albumin excretion rate, ACR, eGFR, creatinine), with most pointing towards a possible increased risk of progression to PDR in people with impaired kidney function." (PMID 36815723, 2023). "Notably, AOPP-modified albumin had a 100-fold greater effect on ROS generation than unmodified albumin, resulting in more severe kidney damage." (PMID 37049779, 2023). "Even after adjustment for all variables correlated with NLR in the previous analyses (age, CVD, duration of CVD, serum albumin, CRP, eGFR, calcium, parathormone, central DBP, cause of nephropathy, ESA), dp-ucMGP, mean BP and gender were strong, independent predictors of NLR." (PMID 36837922, 2023). "In addition, they have well-established renal benefits demonstrated particularly by preventing microalbuminuria and reducing urinary albumin excretion, hence slowing down the progression of nephropathy." (PMID 36294503, 2022). "The albumin that is normally present in the blood during kidney damage is released into the urine." (PMID 36483900, 2022). "In fact, the elevation of BUN, plasma Cr, and reduction of plasma albumin occurs in nephropathy." (PMID 36474578, 2022). "Similarly, in the same gentamicin-induced nephropathy model, the leaf extract of Punica granatum (pomegranate) decreased serum creatinine, urea, and albumin levels as well as urine albumin." (PMID 35336700, 2022). "More than 30 mg/L of albumin indicates kidney damage and the presence of these two crucial complications at the same time in pregnancy may point to preeclampsia." (PMID 36483900, 2022).
kidney damage (continued). "Alterations in any of collagen type IV constituents cause disruption of the GMB structure, allowing leakage of red blood cells and albumin into the urine, and compromise the architecture of the GFB, inducing inflammation and fibrosis, thus resulting in kidney damage and loss of renal function." (PMID 35806283, 2022). "Albumin loss in the urine, morphological changes/glomerular injury, and a reduction in the glomerular filtration rate (GFR) conventionally define this type of nephropathy." (PMID 36139066, 2022). "The albumin excretion rate normally rises steadily over several years as opposed to abruptly changing from normal to abnormal values, which occurs between 10% and 30% yearly until overt nephropathy manifests." (PMID 36046275, 2022). "In addition, hepatic dysfunction, kidney damage, and other conditions can reduce serum albumin levels." (PMID 36407534, 2022). "However, indicators closely related to kidney damage are obviously worse in the patient group, including levels of blood pressure, proteinuria, hematuria, serum albumin, creatinine, and eGFR." (PMID 34979948, 2022). "The results indicate that in absence of Klotho expression in mice, small doses of albumin stimulation for a long time keep burdening the kidney, causing kidney damage." (PMID 33767585, 2021). "Also, albumin has a large number of reduced sulfhydryl groups; therefore, it has an antioxidant effect, which in excess can lead to kidney damage." (PMID 34496793, 2021). "It is called overt nephropathy if the albumin excretion rate is above 300 mg/day." (PMID 34307650, 2021). "In addition, in vitro experiments performed on podocytes, and mesangial and tubular cells challenged with HNA-1 and HNA-2 will provide new possible mechanisms by which oxidized albumin promotes kidney damage." (PMID 33800425, 2021). "Whereas measurement of urinary albumin excretion and fundoscopic examinations serve as objective tests for early nephropathy and retinopathy respectively, a comparably objective, accurate test which is unbiased by the patient’s subjective response is lacking for DPN." (PMID 34122344, 2021). "Low albumin level could reflect an impairment in nutritional status or, in a blood dilution, be a marker that shows kidney damage or the progression of kidney failure." (PMID 34268015, 2021). "Additionally, albumin-to-creatinine ratio is often used to detect albuminuria, which is a marked elevation in urinary albumin levels and a known biomarker of kidney damage." (PMID 35118089, 2021). "Although the determination of glycated albumin is the common approach to the screening, kidney damage may start long before clinically significant changes in urine albumin appear." (PMID 33686844, 2021). "In addition, PRR has recognized as a key component of the intrarenal RAS during albumin overload‐induced nephropathy." (PMID 34057312, 2021). "Increased urine albumin content can directly show kidney damage." (PMID 32686106, 2020). "When DKD patients suffer from kidney damage, as the excretion of urinary albumin increases, the fatty acids filtered by the glomerulus also increase, resulting in excessive free fatty acids bound to albumin being overloaded and reabsorbed in the renal tubules." (PMID 33123032, 2020). "Therefore, effective blood pressure reduction can significantly reduce the occurrence and development of DN, reduce the excretion rate of urinary albumin, and delay the occurrence of decompensated nephropathy." (PMID 32484786, 2020). "This may be explained by the fact that reduced albumin levels in active patients are secondary to kidney damage." (PMID 30884776, 2019). "Aberrant reabsorption of albumin and conjugated FAs has been shown to be toxic to proximal tubule epithelial cells and may contribute to nephropathy progression." (PMID 31373312, 2019).
kidney damage (continued). "Blocking the C5a-C5aR1 axis resulted in a decrease in the albumin-to-creatinine ratio, and the attenuation of kidney damage in IgAN and RSV-IgAN mice might be partly attributed to the inhibition of Th cell and cytokine dysfunction." (PMID 31134161, 2019). "Although hyper-oncotic albumin may minimize lung injury, recent studies have shown that human albumin may lead to kidney damage proportional to albumin concentration." (PMID 31311539, 2019). "Therefore, our study further divided the patients into different groups on the basis of the degree of kidney damage, and investigated the relationships between the indicators and rGFR, as well as that between the indicators and albumin concentration." (PMID 29394255, 2018). "The urinary albumin, blood urea nitrogen, and blood creatinine levels were all reduced with TSF treatment, suggesting that TSF could effectively reduce kidney damage caused by DN." (PMID 29682583, 2018). "However, in a rat model of albumin overload-induced nephropathy, which typically showed increased MCP-1 production in the kidney, the treatment of rats with the functional S1P1 antagonist FTY720 decreased MCP-1 production and mitigated pathological features." (PMID 29772789, 2018). "However, recent data suggest that single urinary albumin measurements are accurate in predicting nephropathy and have been used previously by other investigators." (PMID 28744310, 2017). "To assess whether expression of nephropathy-related mediators involved in renal function and albumin excretion was altered following treatment, we determined their mRNA levels in the kidney." (PMID 27055155, 2016). "Besides this, the elevated levels of WBCs, urinary creatinine, and urea, and decline in creatinine clearance, albumin, and proteins of urine were an indication of severe kidney damage." (PMID 26350293, 2015). "Furthermore, the levels of these substances increase as nephropathy progresses, with an independent relationship between inflammatory parameters and urinary albumin excretion (UAE) suggesting a role of this substances in the pathogenesis of DN." (PMID 25785280, 2015). "In addition, the genetic background (C57BL/6J × 129 SvEv F1) of Akita eNOS −/− mice seems to also be nephropathy-resistant as the urinary albumin excretion in Akita eNOS +/+ mice was less than 100 μg/day even at 7 months of age." (PMID 25371905, 2014). "Moreover, in CKD patients markers of kidney damage (urea, creatinine, albumin and uric acid) were significantly higher than in controls." (PMID 25145866, 2014). "Intermediate-to-high molecular weight proteins such as albumin, if found in urine and not caused by pre- or postrenal factors, are indicative of kidney damage." (PMID 24876663, 2014). "The strong association found between albumin/creatinine ratio and NAG/creatinine ratio perhaps indicates the need for further investigation of the clinical utility of NAG/creatinine ratio as a screening tool for early nephropathy in African diabetics." (PMID 22966455, 2012). "Additionally, it is recommended that glomerular filtration rate be routinely estimated for appropriate screening of nephropathy, because some patients present a decreased glomerular filtration rate when urine albumin values are in the normal range." (PMID 19825147, 2009). "Dogs with membranous glomerulonephropathy had lower serum albumin concentrations (median, 2.1 g/dL; Q1–Q3, 2.0–2.1 g/dL) than dogs with either glomerulosclerosis (median, 3.0 g/dL; Q1–Q3, 2.8–3.3 g/dL; p = 0.01) or other nephropathies (median, 3.0 g/dL; Q1–Q3, 2.6–33.7 g/dL; p = 0.04)." (PMID 40692207, 2025). "Third, urine albumin data were unavailable, and proteinuria assessed by dipstick or urine protein–creatinine ratio was used as a surrogate, which may be less sensitive in detecting early kidney damage." (PMID 41010511, 2025).
kidney damage (continued). "The SAFE trial concluded that albumin was comparable to saline for fluid resuscitation, did not cause notable kidney damage, and might have even reduced mortality risk." (PMID 40841985, 2025). "Therefore, if trace albumin, which is important in determining the second stage of nephropathy, can be detected, it may lead to early detection of the progression of nephropathy." (PMID 39810396, 2025). "Furthermore, acupuncture may decreases urinary albumin secretion, improves renal blood flow and glomerular filtration rate in nephropathy patients or animals." (PMID 39514526, 2024). "After 14 days of FBs exposure, total protein and albumin concentrations fell considerably in the plasma, whereas the plasma creatinine concentration increased, latter is a widely accepted indicator of fumonisin-induced nephropathy (in rabbits:10, in farm animals:37)." (PMID 39107361, 2024). "However, patients with similar levels of urinary albumin excretion may also respond differently, depending on the level of kidney damage prior to treatment." (PMID 35212703, 2022). "Therefore, the synthetic capacity of the liver (which is an estimate of the protein losing nephropathy) may be estimated by the determination of the serum albumin concentration." (PMID 36006215, 2022). "In addition, this prognostic effect could also be explained by the antioxidant effect of albumin and its protection against metabolic acidosis and further kidney damage." (PMID 32776978, 2020). "Thus, our data suggest that iso-oncotic albumin seems to have beneficial effects on brain injury 3 h after an ischemic insult, without being associated with kidney damage." (PMID 33013661, 2020). "We tested the hypothesis that an iso-oncotic solution of albumin (5%), administered earlier after acute ischemic stroke (3 h), could provide neuroprotection without causing kidney damage, compared to a hyper-oncotic albumin (20%) and saline." (PMID 33013661, 2020). "One study identified four Ccl5 gene SNPs that were associated with elevated albumin excretion in non-diabetic patients, which is a prognostic indicator of vascular damage and could lead to nephropathy, a pathological phenomenon driven by CCL5 inflammation." (PMID 32678841, 2020). "However, both in vitro and in vivo studies have shown that human albumin may lead to kidney damage proportional to albumin concentration." (PMID 31311539, 2019). "The final model includes 3 markers of kidney damage (serum creatinine level, serum phosphate level, and urinary albumin-creatinine ratio) plus sex, which may reflect that GFR is lower in women than men for a given creatinine level (and therefore the RR of ESRD for female sex is >1)." (PMID 21035932, 2010). "Rats exposed to either of these halogens also exhibited increased total protein, albumin, and retinol binding protein 4 (RBP4) in the urine indicating significant kidney damage." (PMID 41496587, 2026). "The significant differences observed in age, smoking, drinking, and biochemical markers such as uACR, u-AlB, CREA, and eGFR between the control, DM, and DN groups highlight the progressive nature of kidney damage in DN." (PMID 40958907, 2025). "Odoribacter is a harmful gut bacterium identified in CKD and has been proven to significantly increase the urine albumin-to-creatinine ratio in CKD model mice, indicating a significant role in kidney damage." (PMID 40171160, 2025). "Repeated LPS injection only for seven days induced continued kidney damage in mice, including increased plasma BUN levels and urinary albumin/creatinine (A/C) ratio." (PMID 39716463, 2025). "CKD in individuals with diabetes is diagnosed by the persistent elevation of urinary albumin excretion (albuminuria), low estimated glomerular filtration rate (eGFR), or other manifestations of kidney damage in the absence of signs or symptoms of other primary causes of kidney damage." (PMID 41227173, 2025).